INS (insulin)
Diseases named in the same sentence as INS in open-access papers (continued):
Sharing a sentence is not in itself a finding about the gene and the disease.
metabolic disorders (continued). "The beneficial effect of exercise on the risk of metabolic diseases may be due to the improvement in glucose and insulin sensitivities, inflammatory markers and blood lipids level." (PMID 30219082, 2018). "Insulin secretion from pancreatic β-cells is critical for maintaining glucose homeostasis and deregulation of circulating insulin levels is associated with the development of metabolic diseases." (PMID 30177746, 2018). "CARD9 knockout may ameliorate the metabolic disorders and inflammatory response in insulin susceptible organs in mice after 8–12 weeks of HFD feeding." (PMID 29575791, 2018). "In conclusion, our results that GAA and creatine are associated with specific cardiometabolic risk factors (e.g., fasting insulin, total homocysteine, and body fat percentage) suggest a possible role of these energy-related compounds in the pathogenesis of cardiovascular and metabolic disease." (PMID 29342866, 2018). "Evidence on IGF-1 in relation to metabolic diseases is still controversial, i.e. low levels of IGF-1 have been suggested to have beneficial effects on glucose homeostasis and may also sensitise insulin actions, thereby decreasing metabolic disease risk." (PMID 29618342, 2018). "Fetal insulin is a potent anabolic factor contributing to higher in utero growth and has also been identified as a critical hormone for the early “programming” of later metabolic disease risk." (PMID 30355290, 2018). "It is defined as a “metabolic disorder caused by different factors characterized by a chronic high level of blood sugar with disturbances to carbohydrate, fat, and protein metabolism resulting from defects in insulin secretion, insulin action, or both." (PMID 29202857, 2017). "Moreover, our results in insulin-resistant participants demonstrate the clinical relevance of an intranasal approach for assessing central insulin sensitivity and treating reward dysfunctions in individuals at risk for metabolic disorders." (PMID 28719580, 2017). "Small increases in USP2A protein levels may result in relatively weak expressional changes in metabolic disorder-associated genes in adipose tissue macrophages, followed by gradual changes in insulin sensitivity." (PMID 29138532, 2017). "It was concluded that dietary Se deficiency induces nutritional pancreatic atrophy and metabolic disorder of glucose and lipid in broilers via down-regulation of selenoprotein encoding- and insulin signaling related- genes, indicating potential roles of these genes in metabolic regulation." (PMID 28763492, 2017). "Besides playing important roles in bone metabolism, the Wnt/β-catenin signaling pathway also takes part in glycolysis and regulates mitochondrial physiology and insulin sensitivity and is thus linked to metabolic diseases." (PMID 26801403, 2016). "In accordance with our and others previous work, in the current study weanling pups from obese dams had a greater risk for metabolic disorders, with higher body weights, insulin, glucose, and triglyceride concentrations, and more than doubled WAT mass compared to pups from lean dams." (PMID 25853572, 2015). "In the study carried out by us earlier, it was observed that in AO patients with MS/metabolic disorders carriership of the R223R genotype of the leptin receptor gene was associated with higher BMI and insulin levels; in men it was also associated with larger waist circumference." (PMID 26504811, 2015). "Differences in the effect of fitness on inflammatory status and insulin sensitivity could provide insight into physiological characteristics that influence risk for metabolic disease in response to caloric excess and poor physical fitness." (PMID 22420715, 2012). "Further follow-up and longer-term studies are needed to explore the possibility that insulin sensitization therapy during puberty might reprogramme predisposition to metabolic disease." (PMID 17608755, 2007). "Metabolic disorders associated with elevated insulin levels may be alleviated." (PMID 40241070, 2025).
metabolic disorders (continued). "However, excess intracellular iron stimulates the Fenton reaction and the formation of reactive oxygen species, which is associated with metabolic disorders, affecting mitochondrial functions, lipid metabolism, and insulin signaling, which can lead to cell damage and death." (PMID 40332421, 2025). "IH may induce metabolic disorders by impairing pancreatic β-cell function, causing inflammatory responses in adipose tissue, and increasing glucose production in the liver, which interferes with insulin signaling pathways and disrupts glucose metabolism." (PMID 41133134, 2025). "PLCXD3 expression has an important role in glucose sensing and insulin signaling in pancreatic islet β-cells, and its gene knockdown resulted in a significant decrease in insulin secretion, suggesting a possible association between this gene and metabolic diseases." (PMID 39682314, 2024). "Taken together, increased ST potentially causes increased total body fat and abdominal fat, and the later induces worsening fat mass–insulin resistance vicious cycle in the pediatric and young adult population, therefore ST may be considered an indirect risk factor for metabolic diseases." (PMID 38441224, 2024). "This intervention addressed the effects of an unhealthy diet that may promote the growth of LPS-producing bacteria, leading to LPS translocation caused by intestinal barrier compromise and subsequent metabolic disorders, insulin resistance, systemic inflammation, and immune responses." (PMID 38534735, 2024). "In addition, the altered circadian rhythms and irregular diets associated with shift work and SWSD affect insulin and glucagon secretion, disturbing metabolic homeostasis and increasing the risk of cardiovascular disease and metabolic disorders, which are risk factors for premature ejaculation." (PMID 38961338, 2024). "Moreover, pnpo (sgll) activity in insulin-expressing neurons has been associated with glucose regulation in Drosophila, and there are strong epidemiological links between vitamin B6 deficiency and metabolic disease, making pnpo a relevant candidate to explore." (PMID 38924394, 2024). "Therefore, although BACH1 seems to be associated with metabolic disorders, its specific role in hepatic insulin signaling and glucose homeostasis is unknown." (PMID 38129407, 2023). "Other research has found that compared to mixed or mostly formula infant feeding, it is HIBF that confers the most benefit for improved postpartum insulin resistance and lipid profiles and may underpin the long-term improved risk for metabolic disorders associated with breastfeeding." (PMID 38201858, 2023). "Future clinical trials can explore whether CETP inhibitors can be repurposed to treat metabolic disease and provide an oral therapeutic option to benefit high-risk patients before escalation to injectable drugs such as insulin or glucagon-like peptide 1 (GLP1) receptor agonists." (PMID 37398493, 2023). "In this review, we analyzed the PBG and PI data via the iAUC, potentially masking any significant differences at specific time points (e.g., first-phase insulin response), which could be informative of metabolic disease progression for subjects with or at risk of T2D." (PMID 35388874, 2022). "Recent research suggests that total PA volume accumulated throughout the day may be as important as time spent in moderate-to-vigorous physical activity (MVPA) for lowering markers of metabolic disease risk [e.g., fasting insulin and high density lipoprotein (HDL])." (PMID 34122148, 2021). "Therefore, we speculated that the mechanism of poor prognosis in high-risk patients may be related to the insufficient insulin secretion caused by neuroendocrine abnormality, which mediates metabolic disorders in vivo." (PMID 34090418, 2021).
metabolic disorders (continued). "DM is the known metabolic disease described by elevated blood glucose levels due to compromised metabolism of macromolecules such as carbohydrates, lipids, and proteins and related to absolute or relative deficiencies in insulin secretion or/and insulin action." (PMID 35003299, 2021). "Thus, exploring the effects of BCAA on mTOR and insulin signaling in SAT might provide new perspectives on the nutritional management of dairy cows during periods when they are most susceptible to metabolic disorders." (PMID 34573680, 2021). "As a metabolic disease, the pathogenesis of DM involves multiple factors, such as abnormal genetics and excessive cytokines, and is ultimately characterized by abnormal glucose metabolism due to absolute or relative deficiency and dysfunction of insulin secretion." (PMID 34784849, 2021). "Therefore, it provides a possible explanation that famine might cause the metabolic diseases and their fatal complications by impairing insulin sensitivity and beta cell function." (PMID 32514025, 2020). "Some studies have shown improved insulin sensitivity, weight regulation, and reduced inflammation with increases in gut-derived short-chain fatty acids, all of which may reduce the risk of developing metabolic diseases." (PMID 32210176, 2020). "Therefore, managing postprandial glucose and insulin responses with prebiotic supplements could help decrease the risk of metabolic diseases and also play a role in body weight management in humans." (PMID 27376068, 2016). "The improved insulin sensitivity and glucose tolerance observed in RORγ-deficient mice suggest that the loss of RORγ might be beneficial in controlling glucose homeostasis and in the management of metabolic diseases." (PMID 24831725, 2014). "We then examined whether clozapine also induced changes in mitochondria morphology, membrane potential, and mitochondria volume in the insulin-responsive cell types as these types of changes are thought to underlie the pathogenesis of several metabolic diseases." (PMID 23527073, 2013). "The available clinical guidelines suggest that the pathogenesis of DCD involves several processes, including metabolic disorders, abnormal cerebral insulin signaling, cerebrovascular endothelial damage, neuroinflammation, and neurodegenerative changes." (PMID 41601904, 2026). "Disruption of GM homeostasis can initiate various pathological processes, including metabolic disorders, endocrine imbalances, low-grade inflammation, and reduced insulin sensitivity, thereby providing novel avenues for research into the pathogenesis of PCOS." (PMID 41852411, 2026). "Amylin, co-secreted with insulin by pancreatic β-cells, promotes satiation and is a promising therapeutic target for metabolic disorders." (PMID 41443331, 2026). "The proposed "exercise-EV-mitochondrial adaptation-insulin sensitivity" framework offers a conceptual basis for understanding systemic metabolic adaptation and highlights translational potential for metabolic diseases." (PMID 42290027, 2026). "In contrast, during pathological states, its overexpression exacerbates metabolic disorders by interfering with insulin signaling, inducing endoplasmic reticulum stress (ERS), and suppressing adipose thermogenesis." (PMID 41541675, 2026). "For example, hibernation can serve as a model for understanding metabolic diseases, providing insights into reversible insulin resistance and energy homeostasis." (PMID 41263971, 2026). "Metabolic disorders such as iron overload, glycolysis, insulin resistance, lipid dysregulation, and glutaminolysis are the basis of MASLD." (PMID 39917623, 2025). "IR is a multifactorial metabolic disorder marked by reduced responsiveness of insulin-target tissues (liver, adipose tissue, skeletal muscle) to physiological insulin levels." (PMID 40831951, 2025).
metabolic disorders (continued). "Adiponectin, known for its insulin-sensitizing and anti-inflammatory properties, often evinces low concentrations in obesity, potentially exacerbating metabolic disorders during gestation." (PMID 40427500, 2025). "Inhibiting the RAAS system has the potential to enhance insulin sensitivity and pancreatic β-cell function, ultimately improving abnormal glucose tolerance and metabolic disorders." (PMID 40106408, 2025). "More recently, visfatin has attracted attention due to its insulin-mimetic and pro-inflammatory properties, with emerging relevance in pregnancy-related metabolic disorders." (PMID 40427500, 2025). "The results obtained in insulin-resistant human and animal studies show that using an insulin sensitizer improves insulin sensitivity, alleviates metabolic disorders and ameliorates polycystic symptoms." (PMID 40565151, 2025). "PTP1B is recognized for its adverse regulating influence on leptin and insulin signaling, leading to substantial implications for the development of metabolic diseases." (PMID 40341376, 2025). "Their ability to improve multiple metabolic parameters—including glycemic control, body weight, and insulin sensitivity—further supports their role in the comprehensive management of metabolic disease." (PMID 40289906, 2025). "The intricate interplay between metabolic disorders and AD involves shared mechanisms, including the disruption of insulin signaling, chronic neuroinflammation, and increased oxidative stress." (PMID 40437610, 2025). "Experimental evidence has positioned MIOX as a key regulatory molecule for renal tubular injury in metabolic diseases, with its expression and activity being regulated by fatty acids, insulin, and the mTORC1/SREBP1 pathway." (PMID 41020866, 2025). "T2DM is a metabolic disorder distinguished by prolonged high blood sugar levels and elevated insulin levels stemming from compromised insulin function, secretion, or both factors." (PMID 39941934, 2025). "This developmental plasticity represents both a window of vulnerability, where adverse nutritional or hormonal cues can program future metabolic disease by impairing hypothalamic responses to insulin and leptin, and a window of opportunity for intervention." (PMID 41409607, 2025). "The gut microbiota influences aspects of metabolic disease, including tissue inflammation, adiposity, blood glucose, insulin, and endocrine control of metabolism." (PMID 39235984, 2025). "QUICKI primarily reflects whole-body insulin sensitivity; healthy individuals, compared with those with metabolic disorders maintain insulin sensitivity within normal ranges and exhibit higher baseline QUICKI values." (PMID 41586243, 2025). "The gut microbiota and its metabolites can influence insulin sensitivity and improve metabolic diseases by modulating energy balance as well as lipid and glucose metabolism." (PMID 40332366, 2025). "Environmental endocrine disruptors interfere with RNA modifications involved in insulin signaling, lipid metabolism, and energy homeostasis, leading to metabolic diseases." (PMID 40760453, 2025). "Liposomal systems are most promising for oral and injectable delivery in metabolic diseases, owing to their capacity to improve absorption of poorly soluble drugs and protect peptides such as insulin from degradation." (PMID 41294602, 2025). "Autophagy is also indicated to be disturbed in metabolic disorders like type 2 diabetes, as it has a protective role on β-cell functioning and insulin sensitivity during stress conditions." (PMID 40444035, 2025). "Incorporating polyphenols and phenolic acids into dietary strategies offers significant potential for improving insulin sensitivity, reducing metabolic disorder risks, and promoting whole-body glucose homeostasis." (PMID 40076251, 2025). "This type of metabolic disease is characterized by tissue resistance to insulin and an imbalance in the pancreatic β-cells, which secrete insufficient insulin." (PMID 41020831, 2025).
metabolic disorders (continued). "This chronic inflammation, mainly induced by immune cells, will antagonise insulin sensitivity and, therefore, lead to the pathogenesis of metabolic disorders such as T2DM." (PMID 41226484, 2025). "This exemplifies why single-target approaches such as conventional insulin therapy often fail in complex metabolic diseases." (PMID 41009376, 2025). "ST3GAL5 (GM3 synthase) catalyzes the synthesis of GM3 ganglioside, which is key to regulating insulin sensitivity and inflammation in metabolic diseases." (PMID 41301440, 2025). "It holds distinct advantages in managing metabolic disorders, particularly through modulating gut microenvironment homeostasis, enhancing insulin sensitivity, and promoting insulin secretion." (PMID 41357185, 2025). "DM is a complex metabolic disorder characterised by high blood glucose levels resulting from pancreatic β-cell destruction, peripheral insulin resistance, and compensatory insulin hypersecretion from pancreatic islets." (PMID 39912419, 2025). "T2DM, a metabolic disorder primarily characterized by impaired insulin sensitivity, secretion and action is regarded as a rapidly growing global pandemic." (PMID 41109135, 2025). "Gaining a deeper understanding of these associations through animal models offers crucial insights into potential therapeutic strategies focused on enhancing mitochondrial health and restoring insulin sensitivity in individuals affected by metabolic disorders." (PMID 40862129, 2025). "Interdisciplinary research has revealed that heart, kidney, liver, and metabolic diseases share interlinked pathological mechanisms, including inflammation, oxidative stress, insulin resistance, and endothelial health issues." (PMID 40662045, 2025). "In models of metabolic disease, curcumin has been found to improve glucose tolerance and enhance insulin sensitivity in obese and diabetic rodents." (PMID 41226319, 2025). "This metabolic disorder is primarily manifested through impaired glucose homeostasis, particularly in skeletal muscle and adipose tissue, resulting from defective insulin-stimulated glucose uptake and utilization." (PMID 41450551, 2025). "Some genes are highly involved in insulin secretion regulation, in which CPT1A is associated with the risk of metabolic diseases due to carbohydrate and fat intake." (PMID 41007634, 2025). "The pharmaceutical treatment of metabolic diseases has become a crucial technique, including agents such as insulin sensitizers, lipase inhibitors, xanthine oxidase inhibitors, and farnesoid X receptor (FXR) agonists." (PMID 40564947, 2025). "Insulin resistance (IR) is a central link in metabolic diseases, referring to reduced sensitivity of target tissues to insulin, which impairs glucose uptake and utilization and leads to compensatory hyperinsulinemia." (PMID 41199858, 2025). "Together, these mechanisms illustrate how the lipotoxic environment in metabolic disorders provokes redox imbalance by both fueling ROS generation and activating stress and inflammatory signaling that blunt insulin action." (PMID 41226411, 2025). "DM is a metabolic disease characterized primarily by a chronic increase in blood glucose levels due to insufficient insulin secretion, impaired insulin action, or both." (PMID 41300233, 2025). "Mitochondrial dysfunction in adipocytes impairs lipid metabolism, insulin sensitivity, and thermogenesis, leading to metabolic diseases." (PMID 40577283, 2025). "Through these multiple mechanisms—lipid metabolism, glucose regulation, insulin sensitivity, and inflammation—PPARγ remains a critical target for managing metabolic diseases, particularly T2DM." (PMID 40926269, 2025). "IR, a common pathological basis for both metabolic disorders, impairs the liver’s ability to suppress hepatic glucose production in response to insulin." (PMID 40951422, 2025). "CUL4B plays a significant role in metabolic diseases, particularly in the regulation of adipose tissue and insulin sensitivity." (PMID 40230836, 2025).